TRIM11 (tripartite motif containing 11)
Diseases named in the same sentence as TRIM11 in open-access papers (continued):
Sharing a sentence is not in itself a finding about the gene and the disease.
Cognitive impairment (1 paper, 2020). Abnormal cognition is characterized by deficits in thinking, reasoning, or remembering. "The PSP-subcortical group had a more benign clinical trajectory, less cognitive impairment, lower serum NF-L levels, higher TRIM11 rs564309 minor allele frequency, and more restricted midbrain and cortical atrophy than the PSP-RS and PSP-cortical groups." (PMID 31860007, 2020).
liver diseases (1 paper, 2020). "Lastly, the contribution of AIM2 regulators such as p202, POP3, or TRIM11 to liver diseases is unknown and awaits specific studies." (PMID 32906750, 2020).
melanocytic neoplasm (1 paper, 2025). "Cutaneous melanocytic tumor with CRTC1::TRIM11 fusion (CMTCT) is a rare and recently recognized melanocytic neoplasm with fewer than 50 reported cases." (PMID 41536371, 2025).
metastatic tumors (1 paper, 2022). "TRIM11 was also expressed higher in high metastatic tumors and KDM5C was lower expressed." (PMID 36192394, 2022).
renal carcinoma (1 paper, 2020). A carcinoma arising from the epithelium of the renal parenchyma or the renal pelvis. "Seven genes (TRIM8, TRIM11, TRIM16, TRIM24, TRIM27, TRIM32, and PML) were expressed in different renal cancer cell lines through the KM expression website." (PMID 33173411, 2020).
Richardson syndrome (1 paper, 2025). "TRIM11 is significantly associated with an allele of rs564309 (P = 1.7E-9) in a cohort of PSP patients composed of classical Richardson syndrome (RS) and non-RS." (PMID 40465013, 2025).
sarcoma (1 paper, 2026). A usually aggressive malignant neoplasm of the soft tissue or bone. "In one case, methylation profiling yielded a clear cell sarcoma score of 0.885, just below the confidence threshold, likely due to shared CREB-MITF pathway activation and the lack of a dedicated CRTC1::TRIM11 reference class." (PMID 42015602, 2026).
tumor (32 papers, 2016 to 2026). "In the mouse tumor tissues, Trim11 deficiency also upregulates the expression of Cxcl1, Cxcl2 and Cxcl3." (PMID 36192394, 2022). "Distinction between the two is crucial, as Cutaneous melanocytic tumors with CRTC1:TRIM11 fusion is typically a low-grade neoplasm with good prognosis." (PMID 39420989, 2024). "ACTIN::MITF- and MITF::CREM-rearranged tumors are categorized as melanocytomas in the melanocytic tumors chapter while neoplasms with CRTC1::TRIM11 fusions are classified as malignant soft tissue tumors with uncertain differentiation." (PMID 39264472, 2024). "As a tumor promoting factor, TRIM11 can enhance tumor cell proliferation and invasion through various mechanisms." (PMID 37604203, 2023). "According to GEO Datasets (GSE53819), the mRNA expression level of TRIM11 is higher in NPC tumor tissues compared to normal tissues." (PMID 36376537, 2023). "Another study found that TRIM16, TRIM32, TRIM24, TRIM8, TRIM27, TRIM11, and PML are associated with cancer stem cells and the clinical prognosis of RCC, and affect tumor progression." (PMID 36261847, 2022). "Regarding tumor resistance, TRIM11-mediated drug resistance depends on activating β-catenin/ABCC9 signaling by facilitating the degradation of Daple in NPC." (PMID 36261847, 2022). "Collectively, these results indicate that TRIM11 depletion inhibits tumor growth by regulating the β-catenin pathway in vivo." (PMID 35237324, 2022). "Luo and Wang showed that TRIM11 upregulation was positively correlated with advanced pathological stage, large tumor size, and poor prognosis in GC." (PMID 35237324, 2022). "Both tumor weight and volume were smaller in Trim11+/−MMTV-PyVT mice, supporting TRIM11 as an oncogene." (PMID 36192394, 2022). "Cutaneous melanocytic tumor with CRTC1::TRIM11 fusion (CMTCT) is a newly described neoplasm that falls into the broad category of diagnostically challenging dermal proliferations with melanocytic differentiation." (PMID 34943200, 2021). "Our data indicated that depletion of TRIM11 or YAP by lentivirus-based shRNA inhibited tumor growth, while the overexpression of YAP in TRIM11-knockdown cells partly recovered tumor growth." (PMID 33613102, 2021). "TRIM11 promotes the degradation of misfolded and aggregated proteins in tumor cells’ nucleus or cytosol; for instance, forced expression of TRIM11 was shown to reduce the inclusions formed by Atxn1-82Q and Httax1p-97QP." (PMID 32984318, 2020). "To examine the role of TRIM11 in tumor cells, we implanted HCT116 cells with TRIM11 knockdown or overexpression in immunodeficient mice." (PMID 29581427, 2018). "To further verify the relationship between TRIM11 and miR-24-3p, we detected miR-24-3p expression level by qRT-PCR in the 23 pairs of CC and non-tumor colon tissues, in which TRIM11 expression level had been measured." (PMID 27888625, 2016). "The TRIM11 mRNA level was significantly higher in 22 out of 23 tumor tissues than in the paired normal colon tissues." (PMID 27888625, 2016). "Additionally, TRIM11 can activate MAPK or PI3K/AKT signaling pathways to promote tumor cell proliferation, invasion, and migration." (PMID 37604203, 2023). "It is probably that TRIM11 degrades KDM5C in the nuclei of tumor cells." (PMID 36192394, 2022). "Furthermore, results obtained from xenograft tumor model demonstrated that silencing SOX13 significantly inhibited the tumor growth in vivo and reduced TRIM11 and glycolysis-associated proteins expression." (PMID 35611828, 2022). "In addition, TRIM11 promoted the cell proliferation and invasion capacities of GC cells in vitro and tumor growth in vivo." (PMID 35237324, 2022). "We then used xenograft mice models to further investigate the role of TRIM11 in tumor growth." (PMID 33613102, 2021).
tumor (continued). "Mice treated with DDP or saline were sacrificed 2 weeks after inoculation, and the results showed that the TRIM11 ectopic group (average tumor weight 1.25 g) exhibited significantly enhanced drug resistance compared with the vector group (average tumor weight 0.1125 g) (P < 0.001)." (PMID 32382014, 2020). "In contrast, upregulation of TRIM11 and other TRIMs may contribute to an enhanced cellular capacity to remove misfolded proteins in tumor cells, which enables robust anti-oxidant defense and oncogenic growth." (PMID 29581427, 2018). "Moreover, TRIM11 is required for tumor growth, and increased expression of TRIM11 correlates with poor clinical survival." (PMID 29581427, 2018). "To test whether knocking down TRIM11 suppressed CC tumor growth in vivo, we inoculated nude mice with HT29 and its derived cells." (PMID 27888625, 2016). "Together, these findings indicated that silencing TRIM11 decreased tumor growth in vivo." (PMID 27888625, 2016). "However, co-expression of TRIM11 effectively restored tumor growth." (PMID 29581427, 2018). "Furthermore, knockdown of TRIM11 suppressed tumor growth in vivo." (PMID 27888625, 2016). "miR-24-3p was downregulated in tumor tissues compared with normal colon tissues and TRIM11 was negatively correlated with miR-24-3p expression level (Pearson r = -0.32, P = 0.028), which suggested that the upregulated TRIM11 was, at least in part, due to downregulated miR-24-3p in CC." (PMID 27888625, 2016). "The tumor exhibited diffuse positivity for S-100, SOX10, MITF, TRIM11, and CD68, along with focal positivity for HMB45, MelanA, and CD99, while being negative for ALK." (PMID 40491616, 2025). "Upregulation of TRIM11 enhances the growth and migration abilities of MDA-MB-231 cells, and also promotes tumor growth in vivo, while KDM5C activity inhibits tumor progression and rescues the phenotype caused by TRIM11." (PMID 38769556, 2024). "Meanwhile, silencing SOX13 effectively suppressed the protein level of TRIM11, PCNA and GLUT1, indicating that SOX13 knockdown inhibited growth as well as glycolysis of tumor (**p < 0.01, *p < 0.05)." (PMID 35611828, 2022). "The results showed that TRIM11 knockdown greatly reduced the volume and weight of tumors, and KDM5C knockdown increased tumor growth." (PMID 36192394, 2022). "We found that most of the highly expressed NRGs in tumor tissues have CNV gain, such as TRIM11, ZBP1." (PMID 36059470, 2022). "The result showed that TRIM11 mainly increased in nuclei, and KDM5C was high in the nuclei of normal tissue cells and low in the nuclei of tumor tissue cells." (PMID 36192394, 2022). "The expression of TRIM11 and KDM5C in all tested tumor tissues was correlated, and the p value was very close to the significant value (p = 0.055)." (PMID 36192394, 2022). "However, the role of TRIM11 in the regulation of tumor drug resistance remains unknown." (PMID 32382014, 2020). "To elucidate the impact of TRIM11 on GC tumorigenesis more credibly, we constructed a xenograft model by injecting TRIM11-knockdown MKN-45 cells in the armpit of BALB/C-nude mice and measured the tumor size for 28 days." (PMID 35237324, 2022).
cancer (22 papers, 2018 to 2025). A tumor composed of atypical neoplastic, often pleomorphic cells that invade other tissues. "Surprisingly, TRIMs exhibiting the highest association with cancer include TRIM11, 14, 24, 25, 27, 28, 29, 33, 37, 44, and 59, and each is associated with multiple (at least five) cancers." (PMID 35930602, 2022). "On the contrary, overexpression of some oncogenic TRIMs in various cancers is frequently due to the loss of miR dependent gene suppression (e.g., TRIM11, TRIM14, TRIM24, TRIM25, and TRIM44)." (PMID 33673719, 2021). "Contrary to this, overexpression of some oncogenic TRIMs in various cancers is frequently due to the loss of miR dependent gene suppression as demonstrated—e.g., for TRIM11, TRIM14, TRIM24, TRIM25, and TRIM44." (PMID 33066016, 2020). "Further studies are needed to explore the therapeutic potential of targeting TRIM11 in cancer treatment." (PMID 37604203, 2023). "TRIM11 is one ubiquitin E3 ligase containing ring finger domain and recently reported to be involved in cancer." (PMID 36192394, 2022). "Aberrant expression of tripartite motif 11 (TRIM11) and the Wnt/β-catenin pathway are essential for facilitating tumorigenesis and progression in multiple types of cancer." (PMID 35237324, 2022). "To investigate the roles of TRIM11 and KDM5C in cancer cells, we first constructed stable expressed cell lines of TRIM11 and KDM5C in MDA-MB-231." (PMID 36192394, 2022). "The adjacent genes to the enhancers regulated by KDM5C and TRIM11 were enriched in pathway in cancer, immune response, fatty acid metabolism and wound healing." (PMID 36192394, 2022). "These suggest that TRIM11 regulates H3K4me3 on enhancers of cancer-related genes through targeting KDM5C." (PMID 36192394, 2022). "TRIM11 expression was correlated with progressive cancer stage, higher in all IIA, IIB, IIIA and IIIB stages, while KDM5C behaved the opposite." (PMID 36192394, 2022). "TRIM11 is an E3 ubiquitin ligase and has been reported to act as an oncogene in several human cancers." (PMID 33613102, 2021). "In this way, TRIM11 shows a protective role in the gut, mainly through antagonizing intestinal inflammation and cancer." (PMID 33673719, 2021). "To precisely identify the molecular mechanisms underlying TRIM11-induced ABCC9 expression in NPC, we performed luciferase reporter assays to assess the effect of TRIM11 on important cancer pathway." (PMID 32382014, 2020). "In terms of intestinal inflammation and cancer, a direct contribution of autophagy has been demonstrated for TRIM11 and TRIM14." (PMID 33066016, 2020). "From their data, it is tempting to suggest that TRIM11 exerts a protective role in the gut mainly through antagonizing intestinal inflammation and cancer." (PMID 33066016, 2020). "Tripartite Motif Containing 11 (TRIM11), an E3 ubiquitin ligase, is identified as a carcinogen causing certain human cancers." (PMID 31950060, 2019). "TRIM11 exerts certain carcinogenic effects in a variety of cancers." (PMID 36376537, 2023). "This infers that TRIM11 is potential targets to be used in the treatment of NSCLC or other cancers." (PMID 37604203, 2023). "These suggest TRIM11 regulates immune gene expression through targeting KDM5C, which may serve as a new mechanism for TRIM11’s function in cancer immune response." (PMID 36192394, 2022). "For cancer subgroups, TRIM11 and KDM5C were significant correlated in Her2 subgroup." (PMID 36192394, 2022). "TRIM11, an E3 ubiquitin ligase, has been discovered to facilitate various cancers progress." (PMID 35611828, 2022). "Additionally, TRIM11 functioned as an oncogene in GC cells, and its cancer-promoting effects were mainly mediated by the Axin1-β-catenin axis." (PMID 35237324, 2022).
cancer (continued). "TRIM11 is found in neurons of the cerebellum and basal ganglia in healthy adults and is also is expressed during development to regulate stem-like factors, as described in the section above on cancer, with TRIM11 knockdown resulting in the accumulation of cytotoxic insoluble aggregates of PAX6." (PMID 38115822, 2023). "Thus, properly adjusting the levels of TRIM proteins in general and TRIM11 in particular may be beneficial in treating both cancer and neurodegeneration." (PMID 29581427, 2018). "It has been shown in previous studies that the E3 ubiquitin ligases, such as RNF146, TRIM11, TRIM32, TRIM54, TRIM65 and UBE3C promote various cancers by triggering Wnt/β-catenin signaling via degradation of Axin1." (PMID 37379772, 2023). "TRIM11 can also promote proliferation, migration and EMT by activating the beta-catenin signaling in cancer." (PMID 36461099, 2022). "Inhibition of TRIM11 may be a potential strategy for the treatment of early‐stage NSCLC and other cancers." (PMID 37604203, 2023). "TRIM11, TRIM27, TRIM28 and TRIM59 have higher expression in almost all cancers." (PMID 36461099, 2022). "In recent years, many research studies have shown that TRIM family proteins, such as TRIM3, TRIM11, TRIM19, TRIM31, TRIM44 and TRIM59 have been demonstrated to serve a significant role in the tumorigenesis and progression of numerous cancer types." (PMID 30484263, 2019). "In addition, TRIM proteins (TRIM11/25/26/28/33/59/62/66/72) and TGFB pathways (Smad4 degradation) have been shown to promote epithelial–mesenchymal transition, cell migration, and invasion of cancer cells through activation of the TGF-β signaling pathway." (PMID 40338274, 2025). "Hence, TRIM11 is a potential target for the treatment of NSCLC and other cancers." (PMID 37604203, 2023).
infection (3 papers, 2013 to 2016). The state of being infected such as from the introduction of a foreign agent such as serum, vaccine, antigenic substance or organism. "To confirm the negative regulation of IFNβ production by TRIM11, we prepared TRIM11-knockdown 293T cells by infection with lentivirus encoding one of two different shRNAs against TRIM11 and isolated stably infected cells by puromycin selection." (PMID 23675467, 2013). "The results presented above indicated that TRIM11 recognizes HIV-1 capsid during infection and accelerates viral uncoating, resulting in reduced reverse transcription." (PMID 27737691, 2016). "We found that pelletable capsid levels were significantly lower in TRIM11 overexpressing cells than that in vector control cells since 2 h post infection." (PMID 27737691, 2016). "More importantly, our results imply that the HIV-1 accessary protein, Vpr, can regulate TRIM11 protein levels during infection." (PMID 25105968, 2014). "The results of the dose-course infection experiments were consistent with the results from the Vpr and TRIM11 cotransfection experiment." (PMID 25105968, 2014). "Furthermore, knockdown of TRIM11 enhanced HIV-1 reverse transcription levels as well as HIV-1 capsid stability by about 50 % at 1 h post infection." (PMID 27737691, 2016). "To further confirm the effect of TRIM11 on viral infectivity, we tested culture supernatants from TRIM11-knockdown cells in HSV-1 and VSV-GFP infection assays." (PMID 23675467, 2013). "As expected, treatment with culture supernatants from TRIM11-knockdown cells more efficiently prevented HSV-1 and VSV-GFP infection than those from control cells." (PMID 23675467, 2013).
TRIM11 also shares sentences with these, for which no sentence is quoted: pancreatic ductal adenocarcinoma (3 papers); neurodegenerative disease (2); anaplastic cancer (1); diabetic nephropathy (1); Epithelioid Malignant Peripheral Nerve Sheath Tumor (1); follicular thyroid cancer (1); Hypertension (1); lung adenocarcinoma (1); mesenchymal tumors (1); microcephaly (1); pancreatic cancer (1); papillary thyroid cancer (1); Parkinson disease (1); perivascular epithelioid cell neoplasm (1); protein (1); renal clear cell carcinoma (1); retinal disease (1); spindle cell neoplasm (1); triple-negative breast carcinoma (1).